IL6 (interleukin 6)
Diseases named in the same sentence as IL6 in open-access papers (continued):
Sharing a sentence is not in itself a finding about the gene and the disease.
tumor (continued). "In the immune system, MAGI2-AS3 could modulate genes related to immune cell activation and cytokine production, such as IL-6 and TNF-α, which are crucial in tumor-associated inflammation." (PMID 40687762, 2025). "Notably, MC function is dynamically regulated by tumor micro-environmental signals: IL-1, IL-4, IL-6, and TNF-α activate antitumor effects, whereas VEGF, matrix metalloproteinase, trypsin-like enzymes, and IL-10 promote malignant progression." (PMID 40960294, 2025). "IL6-induced Snail overexpression is also associated with increased transcription, expression, and activity of MMP2 in epithelial cells, causing degradation of the basement membrane and facilitating the successful invasion and metastasis of tumor cells." (PMID 40427188, 2025). "Biologically, an elevated monocyte burden reflects enhanced recruitment of circulating monocytes into the tumor microenvironment, where they differentiate into TAMs under the influence of cytokines such as IL-6, transforming growth factor-β (TGF-β), and colony-stimulating factor-1 (CSF-1)." (PMID 41487591, 2025). "EMT interacts with the microenvironment: EMT-transformed cells activate tumor-associated fibroblasts (CAFs) by secreting factors such as TGF-β and IL-6, which in turn secrete HGF and FGF, maintaining the EMT phenotype through c-Met/FGFR signals, forming a positive feedback loop of drug resistance." (PMID 41293424, 2025). "Study found inhibiting IL6 could also reduce activity of NF-κB pathway, lower production of inflammatory mediators and mitigate the pro-inflammatory state within tumor microenvironment." (PMID 40535567, 2025). "ELISA results indicated that the baseline secretion of IL-6 in the CM from i1BR3 cells was comparable to that from primary 1BR3 cells and that Fb secreted IL-6 at a rate approximately five times higher than that of the tumour cell lines." (PMID 39858048, 2025). "CXCL-7 interacts with tumor cells and promotes further synthesis of interleukins IL-6 and IL-8." (PMID 41471830, 2025). "Interestingly, in the prostate, ERα expression in CAFs can inhibit IL6 expression, thereby suppressing the formation of an immunosuppressive environment and controlling tumor progression." (PMID 40007149, 2025). "In addition, tumor-produced IL-6 has been shown to reduce the expression of MHC-II in myeloid cells in the TME, which can be recovered by IL-6R blockade." (PMID 39653766, 2025). "In line with J. Sun’s findings, we believe that a balanced state could indicate a favorable postoperative prognosis; our data suggest that an increase in the pro-inflammatory state (IL-6/IL-10 ratio) is a strong predictor of tumor recurrence." (PMID 40227646, 2025). "Furthermore, the elucidation of complex signaling pathways, such as the IFN-I → B-cell → IL-6 → Th17 axis, reveals the precise communication network through which the anti-tumor response fosters a pro-inflammatory environment that is catastrophic for the CNS." (PMID 40963604, 2025). "IL-6 promotes tumor growth and therapeutic resistance by enhancing inflammation and immune evasion." (PMID 39857670, 2025). "Consistent with clinical findings, treatment using a humanized anti‐IL‐6 monoclonal antibody to globally block IL‐6 has shown protection against loss of LBM—a key measure of cachexia—without affecting tumor progression." (PMID 39764565, 2025). "Moreover, depression promotes tumor-associated macrophage infiltration through neuropeptide Y signaling and accelerates tumor progression via activation of the IL-6/STAT3 pathway." (PMID 41409248, 2025). "Additionally, sorafenib inhibits STAT phosphorylation mediated by IFNα and IL-6, reducing PD-L1 expression and consequently diminishing tumor immune evasion." (PMID 40102789, 2025). "Tregs, tumor-associated macrophages, and myeloid-derived suppressor cells inhibit T-cell activity via PD-1/PD-L1 and CTLA-4/CD80/86 pathways, while OSCC cells release VEGF, TGFβ, IL-6, and IL-10 to suppress immunity." (PMID 40924302, 2025).
tumor (continued). "Butein may paradoxically enhance IL-6 under hypoxic or tumor-stimulated environments, raising concerns about dose, context, and cell type specificity." (PMID 40917888, 2025). "Altogether, the actions of EVs ensure that the pre-metastatic niche is rich in growth-permissive signals (e.g., fibronectin, S100 proteins, VEGF), pro-inflammatory mediators (e.g., TNF-α, IL-6) that paradoxically aid tumor development, and immunosuppressive cell populations." (PMID 40574836, 2025). "Similarly, IL-6 produced by CAFs exerts paracrine effects distinct from tumor-derived IL-6, preferentially activating STAT3 signaling in adjacent immune and epithelial cells." (PMID 41179287, 2025). "However, cytokines secreted by tumor cells, such as G-CSF, IL-1β, IL-6, and TNF, can extend their longevity." (PMID 41280929, 2025). "Importantly, in addition to its antitumor role, the immune system can stimulate tumor growth through signaling with certain cytokines (IL-1β, IL-23, IL-11, IL-6, TNF, and GM-CSF)." (PMID 40697381, 2025). "In cancer, both IL-6 and IL-1β promote tumor growth and enhance invasiveness." (PMID 41294748, 2025). "Disrupting astrocyte-tumor crosstalk by targeting IL-6, TGF-β, and their receptors with monoclonal antibodies may suppress astrocyte activation and help delay the development of drug resistance." (PMID 40149331, 2025). "Furthermore, both IL6 and CCL20 are implicated in promoting monocyte migration, a key factor in the inflammatory tumour environment." (PMID 40913253, 2025). "Programmed death-ligand 1 (PD-L1): CAF-mediated cytokines such as IL-6 and IL-8 can upregulate the expression of PD-L1 on tumor cells, and interaction of PD-L1 and PD-1 on TILs leads to TIL exhaustion, characterized by reduced cytotoxic activity and diminished production of effector molecules." (PMID 40805183, 2025). "We postulated that the IL-6 identified in our data might interact with IL6ST expressed in tumor cells, immune and stromal cells." (PMID 39762212, 2025). "In addition, TNF-α, IL-1β, and IL-6 have been demonstrated to suppress cell mediated immunity and promote intravascular tumor cell adhesion." (PMID 40427164, 2025). "Also, IL-6 has been reported to play an important role in the induction of the immunosuppressive tumor microenvironment." (PMID 40317079, 2025). "The current study hypothesizes that cisplatin influences the immunomodulatory functions of MSCs via suppression of the tumor promotors IL-6 and IDO." (PMID 40699630, 2025). "Additionally, from diagnostic perspective, our ROC curve analysis indicated that TNF-α, IL-6 and IL-12 had the strongest ability to discriminate tumour tissue from the corresponding surgical margins (AUC 0.76, 0.65 and 0.65, respectively)." (PMID 41465261, 2025). "Patients with metastatic PC typically have higher serum levels of IL-6, which may speed up tumor growth over time." (PMID 39891849, 2025). "IL-6 influences tumor progression through chemotactic MDSCs in the TIME." (PMID 41326342, 2025). "Similar to IL-6, IL-8 can have dual roles; while it recruits immune cells to the tumor microenvironment, it may also contribute to an immunosuppressive environment that allows tumors to evade immune detection." (PMID 40573301, 2025). "In addition, IL-6 aids in the immune response by increasing antibody production, which results in anti-tumor and anti-inflammatory benefits." (PMID 40724351, 2025). "Since IL6 is a pro-inflammatory cytokine known to promote cancer metastasis and induces PD-1 expression in activated T cells, blocking IL6 pathway may reduce tumor immune escape in TME and enhance anticancer immunity." (PMID 39996058, 2025). "Monocytes, either directly or through differentiation into dendritic cells or tumor‐associated macrophages (TAMs), contribute to tumor growth by enhancing VEGF production, releasing IL‐6 and IL‐1, and suppressing cytotoxic T cell responses via IL‐10 and transforming growth factor‐beta (TGF‐β)." (PMID 41307215, 2025).
tumor (continued). "At the same time, IL-6 can inhibit anti-tumor immune responses." (PMID 41376630, 2025). "In turn, the cytokines produced by activated macrophages could further activate NF-κB and increase the expression of various inflammatory and tumor-promoting cytokines (such as IL-6, IL-1α, and TNF-α) and genes such as BCL-2 and BCL-XL." (PMID 40109347, 2025). "Additionally, extracellular vesicles released by OS can shift MSCs towards a pro-tumor phenotype, characterized by a high production of IL-6." (PMID 40149640, 2025). "While M2 macrophages promote tumor growth, angiogenesis, and immune suppression, M1 macrophages foster inflammation and induce tumor cell death by releasing cytotoxic molecules (e.g., IL-1β, IL-6, caspases)." (PMID 40870970, 2025). "Future studies could incorporate H. pylori status or measure additional cytokines (like IL-1β, IL-6) to dissect the contributions of tumor versus background inflammation." (PMID 40299527, 2025). "TLRs activate inflammatory responses but can also promote tumor-supportive cytokines like IL-6." (PMID 41157253, 2025). "Additionally, the ability of tumor cells to secrete substantial quantities of IL-6, triggered by hypoxia and ER stress inducer, was suppressed in an in vitro model following the utilization of the IRE1α-XBP1s pathway inhibitor, 4μ8C." (PMID 41254082, 2025). "In a high-fat microenvironment, IL6 produced by fat acts on tumor cells." (PMID 40841364, 2025). "Notably, increasing evidence highlights aberrant activation of the IL-6/STAT3 signaling pathway as a key contributor to tumor growth and resistance to therapy in cancer." (PMID 41148817, 2025). "Preclinical validation is provided by studies such as one employing a murine model of breast cancer, where regular endurance exercise training significantly mitigated the elevated systemic levels of key inflammatory mediators MCP-1 and IL-6 observed during tumor development." (PMID 40900783, 2025). "In addition, the TAM-secreted IL-6 stimulated the JAK2-STAT3 pathway in tumor cells and then upregulated the expression of CCL2 and EIF4A3." (PMID 40443670, 2025). "A wide range of CAF-derived molecules—including cytokines (e.g., interleukin-6 [IL6], transforming growth factor-β), growth factors, proteases, and matricellular proteins—have been shown to enhance tumor proliferation, invasion, angiogenesis, and immune evasion." (PMID 41465449, 2025). "In addition, CAFs have secretory functions, releasing various factors that modulate tumor cells, including transforming growth factor-β (TGF-β) and the interleukins IL-6 and IL-8, amongst others, which provide supportive drivers for tumor metastasis 11-13." (PMID 40612679, 2025). "By attenuating IL-1β, IL-6, IL-8 and related chemokines, statins may weaken the inflammatory pathways that sustain tumour growth and immune evasion in cancer and strengthen the efficacy of therapeutic regimens in cancer patients." (PMID 40943351, 2025). "Furthermore, we also analyzed the expression of TNF‐α, IL‐6, and IL‐10 genes in tumor tissues, which were consistent with the ELISA results, with the most significant changes observed in the CB‐AKK combined group improved by 19 times." (PMID 40497373, 2025). "IL-6, though associated with tumor progression via STAT3 activation, can initiate negative feedback through SOCS3 or STAT3 degradation during acute stress." (PMID 41401147, 2025). "SASP-mediated tumor suppressive functions, such as the secretion of interleukin-6 (IL-6), interleukin-8 (IL-8), plasminogen activator inhibitor-1 (PAI-1), and insulin-like growth factor-binding protein 7 (IGFBP7), enhance senescence arrest in in vitro experiments." (PMID 40722797, 2025). "The presence of micrometastatic tumor cells in the liver may also activate Kupffer cells to produce a variety of cytokines (IL-1b, IL-6, TNF), which regulate albumin synthesis by hepatocytes." (PMID 40004975, 2025).
tumor (continued). "Notably, our previous studies confirmed that tumor-derived IL-6 significantly induced tumor growth and metastasis by promoting MDSC recruitment." (PMID 41326342, 2025). "In this study, 24 h after central nervous system (CNS) ischemia, the concomitant inflammatory cascade response with elevated levels of tumor necrosis caused systemic peaks of TNF-α, IL-1β, and IL-6, and pre-administration of GJC-CDs reduced the levels of related inflammatory factors." (PMID 40573265, 2025). "In addition, in BC patients, cytokine secretion, including IL-6, IL-8, and monocyte chemotactic protein-1 (MCP-1), is significantly elevated in tumour-associated adipose tissue." (PMID 40414892, 2025). "However, M2-like TAMs enhance tumor cell survival by secreting IL-6 and TGF-β, which activate DNA repair pathways such as MGMT and PI3K/Akt/STAT3, leading to increased TMZ resistance." (PMID 41002423, 2025). "Finally, the alliance of CAR-Ts with CAR-Ms remodulates the TME to the detriment of the tumour via a large cytokine network including IL-6, IL-1β, and IFN-γ." (PMID 40574837, 2025). "Other TGs, such as TGM2, modulate IL6 expression in various cancers, promoting tumor progression." (PMID 41425727, 2025). "In addition, it has been demonstrated that tumor-derived IL-6 suppresses PPARα, one of the major regulators of hepatic ketogenesis." (PMID 41218549, 2025). "This defines the tumor-suppressing effect of IL-6 during early stages of tumor development." (PMID 41376623, 2025). "The janus kinase/signal transducers and activators of transcription signaling pathway plays a pivotal role in the polarization of M2 macrophages, mediated by cytokines such as interleukin-4 (IL-4), IL-6, and interleukin-13 (IL-13), which modulate immune responses and facilitate tumor escape." (PMID 40098971, 2025). "Activated platelets serve as indicators of inflammation, secreting multiple cytokines essential for tumor cell growth, including interleukin-6 (IL-6), vascular endothelial growth factor (VEGF), platelet-derived growth factor (PDGF), and transforming growth factor-beta (TGF-β)." (PMID 40472013, 2025). "Additionally, in the LUAD mice model, IL-17A was demonstrated to promote tumor growth by inducing IL-6." (PMID 41376623, 2025). "IL-6 expression dominates in the tumor microenvironment (see review)." (PMID 40264585, 2025). "However, studies suggest that reduced IL-10 expression permits increased angiogenesis and heightened activity of VEGF, IL-1β, TNF-α, IL-6, and NF-κB, ultimately enhancing tumor growth." (PMID 40100373, 2025). "Moreover, tumor cells can produce cytokines such as TGF-β, IL-10 or IL-6, that can contribute to immune suppression and tumor progression through the inhibition of T cell activity and the promotion of the differentiation of Tregs." (PMID 40805123, 2025). "Interestingly, high IL-6 expression in OSCC tumours was shown to predict worse disease-free survival." (PMID 41271789, 2025). "Emerging evidence indicates that periodontal pathogens, particularly P.g., may undermine efficacy of conventional anti-cancer therapies by promoting chemoresistance and enhancing tumor adaptability via pathways regulated by Notch1 and IL-6." (PMID 40924302, 2025). "SASP components, including IL-6, IL-8, MMPs, and growth factors, provide a pro-inflammatory and pro-tumorigenic milieu that fosters tumor heterogeneity, immune evasion, EMT, and the reprogramming of adjacent non-senescent cells into more plastic or stem-like states." (PMID 41013839, 2025). "CRP release is stimulated by IL-6, which also controls stromal desmoplasia, encourages tumor-induced immunosuppression and angiogenesis, suppresses apoptosis, increases the proliferation of cancer cells, and aids in metastasis, including the creation of a pro-metastatic niche in the liver." (PMID 40842988, 2025). "Moreover, in HPV-positive BC patients, tumor tissue exhibits higher levels of IL-6, IL-17, TNF-α, and TGF-β, along with activation of NF-κB and STAT3." (PMID 41597595, 2025).
tumor (continued). "Furthermore, Il-6 mRNA expression at the tumor site was increased 2-fold in Cx- compared to pre-Cx mice, while Gdf15 mRNA level remained unchanged." (PMID 40124481, 2025). "This epigenetic modification represses anti‐tumor genes while activating IL‐6/STAT3 signaling." (PMID 40904700, 2025). "Notably, both recombinant IL-6 and tumor-conditioned medium substantially diminished the cytotoxic activity of human peripheral blood NK cells against A549 cells." (PMID 41254082, 2025). "In addition, IL-6 promotes STAT3 activation in Tumor Cells, thereby enhancing their resistance to apoptosis and increasing their proliferation rate." (PMID 41333481, 2025). "In the TME, IL6 is required to promote angiogenesis, the formation of new blood vessels from existing ones, which is critical for tumor survival, providing essential pathways for a continuous supply of nutrients and the removal of waste products to sustain their rapid growth and survival." (PMID 40427188, 2025). "Research on IL-6 and tumor immunity has also significantly progressed in recent years." (PMID 40433391, 2025). "Neutrophil-secreted IL-6 enhances tumour cell survival by conferring resistance to apoptosis." (PMID 41451221, 2025). "The role of the IRE1α/XBP1 signaling in the activation of IL-6-JAK-STAT signaling is also supported by the finding that myofiber-specific deletion of XBP1 strongly inhibited the phosphorylation of STAT3 in skeletal muscle of KPC tumor-bearing mice." (PMID 40655023, 2025). "In addition, polarized M2 macrophages enhance phosphoglycerate kinase 1 (PGK1) threonine (T) 243 phosphorylation in tumor cells by secreting IL-6." (PMID 40131539, 2025). "Additionally, KPNA2 from BCa cells triggered the conversion of fibroblasts into cancer-associated fibroblasts (CAFs), which secreted elevated levels of interleukin-6 (IL-6), contributing to a tumor-supporting environment." (PMID 39956902, 2025). "Furthermore, antibody-antigen immune complexes engage Fcγ receptors on myeloid-derived suppressor cells and TAMs, amplifying immunosuppressive cytokine networks (e.g., IL-6, IL-8) while triggering chronic inflammation that fosters tumor niche establishment." (PMID 41246318, 2025). "IL-6 is a key pro-inflammatory cytokine produced by tumor cells, fibroblasts, and immune cells." (PMID 41394847, 2025). "IL-6 is a pro-inflammatory cytokine that is mostly produced by monocytes and macrophages, although it can also be secreted by T lymphocytes, B lymphocytes, hepatocytes, fibroblasts, keratinocytes, endothelial cells, mesangial cells, and other tumor cells." (PMID 40938862, 2025). "As commented on earlier, tumours actively secrete a variety of cytokines and pro-inflammatory mediators, including IL-6, TNF-α, and IL-1β, which can reach the adipose tissue and trigger the recruitment of immune cells, such as macrophages and T cells, leading to a chronic inflammatory state." (PMID 41373779, 2025). "In addition, Western blot results indicated that compared to the oe‐NC group, the expression of pro‐inflammatory cytokines IFN‐γ, IL‐12, and IL‐6 increased in the tumor tissues of mice in the oe‐NC+M2pep‐Cs NPs/Plerixafor group." (PMID 40536774, 2025). "By stimulating anti-apoptotic and angiogenic pathways, IL-6 contributes to tumor advancement." (PMID 40149421, 2025). "Tumour burden is reduced in IL-6 knockouts while increasing IL-6 accelerated tumour formation." (PMID 40381373, 2025). "This substantial decrease in IL-6 concentration suggests that ADSC-EVs may exert anti-inflammatory or tumor-suppressive effects on MCF-7 cells." (PMID 41514893, 2025). "However, a persistent SASP can drive immune exhaustion and chronic inflammation, suppressing anti-tumor responses through elevated levels of IL-6 and TGF-β." (PMID 40277933, 2025). "Tumor-associated myeloid cells and microglia (TAMs) (key components of the GBM microenvironment) contribute to GBM progression by secreting cytokines and chemokines, such as PDGFB, EGF, SDF-1α, IL-6, and IL-8." (PMID 40867240, 2025).